TPO (thyroid peroxidase)
Diseases named in the same sentence as TPO in open-access papers (continued):
Sharing a sentence is not in itself a finding about the gene and the disease.
hypothyroidism (continued). "In 22 women with overt hypothyroidism, 14 (63.64%) exhibited a significant elevation of anti-TPO and anti-TG (P = 0.041, P = 0.008), respectively." (PMID 37606882, 2023). "Similar to these findings, autoimmune comorbidities in our patients included hypothyroidism (10%), elevated anti-TPO antibodies (5%), and RA (10%)." (PMID 37323348, 2023). "Hashimoto’s thyroiditis is defined by the presence of high serum thyroid antibody concentrations (anti-Tg and/or anti-TPO) accompanied by hypothyroidism or goiter." (PMID 37716983, 2023). "This would prevent long-term morbidity since anti-TPO antibody is related to future overt hypothyroidism and other autoimmune diseases." (PMID 38289816, 2023). "One way to investigate the mechanistic relationship between hypothyroidism and mood disorders is to perform genetic correlation analyses on TPO antibodies and mood disorders." (PMID 36463425, 2023). "After ruling out other possible diagnoses, we confirmed the presence of HT based on positive anti-TPO test results, global hypokinesia of the left ventricle, and biochemical hypothyroidism." (PMID 37861476, 2023). "In patients with elevated anti-TPO Ab levels, hypothyroidism prevalence was higher in patients with PCOS versus patients without PCOS." (PMID 37635968, 2023). "The prevalence of positive anti-TPO was accompanied by a steadily advancing clinical deterioration of hypothyroidism (17.83% in euthyroid, 56.86% in subclinical hypothyroid, and 63.64% in overt hypothyroid women)." (PMID 37606882, 2023). "It was further observed that hypothyroidism prevails in patients with Graves’ disease undergoing partial thyroidectomy in the setting of positive anti-TPO Abs." (PMID 37123800, 2023). "It was concluded that there was a trend of increased incidence of new cases of thyroid disorder, hypothyroidism, and anti-TPO positivity, particularly in female subjects versus controls." (PMID 38192953, 2023). "Chronic autoimmune thyroiditis (Hashimoto’s thyroiditis), characterized by anti- thyroid peroxidase (TPO-Ab) and anti-thyroglobulin (Tg-Ab) antibodies in more than one-third of patients can occur, and present with either subclinical or overt hypothyroidism." (PMID 36612243, 2022). "The patients with positive TPO represent 28% of the total cohort including probands and subsequent siblings (n = 28) but among those, only 4 patients had clinical hypothyroidism on treatment." (PMID 35802651, 2022). "Thyroid peroxidase antibodies (TPO Abs) are associated with autoimmune thyroid disease, and their measurement is helpful in the diagnostic workup of hypothyroidism." (PMID 35687484, 2022). "The European experts recommended that testing for hypothyroidism is based on the level of thyroid-stimulating hormone level; if this is increased, free thyroxine and antibodies (anti-thyroid peroxidase) should be measured." (PMID 35579858, 2022). "Patients with subclinical hypothyroidism with elevated anti-TPO and anti-Tg antibodies are more likely to progress to clinical hypothyroidism." (PMID 36506504, 2022). "They found that TPO antibodies were observed among 42.2% of patients, with 2.1% diagnosed with overt hypothyroidism." (PMID 36039251, 2022). "Patients with AITD, often exhibit auto-antibodies such as anti-thyroglobulin (Tg-Ab) and anti-thyroid peroxidase (TPO-Ab) antibodies, and the same AITD is strongly associated with hypothyroidism condition." (PMID 36465640, 2022). "In this study, the prevalence of hypothyroidism was 16.3%, and TPO positivity has been detected in 58.6% of diabetic type 1 patients." (PMID 36039251, 2022). "Patients with HT are typically presented with hypothyroidism, goiter, and increased thyroid peroxidase antibody level." (PMID 35768466, 2022). "Among the 13 women with TPO-AB >60 U/mL, prevalence of hypothyroidism was significantly higher than in women with TPO antibodies in the normal range (61.5% versus 13.8%; p < 0.001)." (PMID 35453500, 2022).
hypothyroidism (continued). "For patients with hypothyroidism, most patients will have positive thyroid peroxidase antibody, TH decreased and abnormal immune function, which will further affect the utilization of insulin in peripheral tissues." (PMID 35419407, 2022). "Thyroperoxidase antibodies (TPO, at the time of hypothyroidism) were positive (216 kUI/L, reference range: < 34), while the TSH receptor antibodies (TRAb, analysis of stimulating or blocking) were negative." (PMID 36419114, 2022). "In bivariable analyses, the 15 participants with overt hypothyroidism had significantly higher prevalence of anaemia and anti-TPO positivity than the euthyroid participants." (PMID 36083409, 2022). "At irAE onset, the two patients developing hypothyroidism had normal to undetectable autoantibodies against thyroid peroxidase and thyroglobulin." (PMID 35017151, 2022). "HT was clinically diagnosed based on hypothyroidism, elevated thyroglobulin antibodies (TG-Ab) and thyroid peroxidase antibodies (TPO-Ab), inhomogeneous parenchyma on ultrasonography, and lymphocytic infiltration on cytology." (PMID 36686823, 2022). "In conclusion, this study demonstrated that RA disease was an independent covariant for thyroid dysfunction (especially for overt hypothyroidism), presence of anti-TPO positivity, and AITD among the Iranian population like several other populations." (PMID 36274180, 2022). "The prevalence of hypothyroidism was 16.3%, and TPO positivity was discovered in 58.6% of the tested patients (n = 70) with equal prevalence among both genders (p = 0.685)." (PMID 36039251, 2022). "Many authors have reported the occurrence of hypothyroidism and raised anti-TPO Ab titers amongst women with GDM." (PMID 35165548, 2022). "Women with euthyroid status but with raised anti-TPO Ab positivity should ideally be followed up for more rigorous assessment of hypothyroidism in subsequent pregnancies." (PMID 35165548, 2022). "Many studies conducted in non-pregnant states reported a positive association between either overt or subclinical hypothyroidism or autoimmune stigmata of thyroiditis (positive anti-TPO antibodies) with anxiety, whereas others did not." (PMID 34421508, 2021). "Women with high TSH and low-free T4 (overt hypothyroidism) were further subjected to thyroid peroxidase antibodies (TPO-Ab) estimation." (PMID 33524025, 2021). "TPO antibody was positive among 57.1% of women with hypothyroidism (p = 0.012) and 7.1% in euthyroid women." (PMID 33524025, 2021). "Approximately 30% (15/49) of women with a clinical history of hypothyroidism had positive TPO antibodies at baseline compared to 7% (20/272) of those with no prior history of thyroid dysfunction (p < 0.001)." (PMID 34771605, 2021). "The pSS has a close correlation to hypothyroidism with increased anti-thyroid antibodies (anti-TPO, anti-TG)." (PMID 33917955, 2021). "In the control group, 7 (2.8%) had hypothyroidism, one (0.4%) hyperthyroidism, 242 (96.8%) normal thyroid function, and one positive anti-TPO result (0.4%)." (PMID 32190224, 2020). "Elevated levels of TPO antibodies were found in 9 of 18 patients (50.0%) with hypothyroidism vs 5 of 45 patients (11.1%) with normal thyroid function (P < .001)." (PMID 32202644, 2020). "The multivariate analysis showed that TPO-Ab, TG-Ab, TG, and Fb were independent predictors of hypothyroidism." (PMID 32461982, 2020). "The ROC curves showed that the effect of combining TPO-Ab, TG-Ab, TG, and Fb with the four indexes to predict the incidence of hypothyroidism was significantly higher than that of their independent prediction (AUC = 0.796)." (PMID 32461982, 2020). "One patient developed hypothyroidism due to autoimmune thyroiditis (anti-TPO levels > 1000 U/mL) during treatment with SSA; at T1, all 3 patients were adequately substituted with levothyroxine for more than 3 months." (PMID 31612224, 2020). "Children with overt hypothyroidism were younger (10.6 vs. 13.2 years) and had higher thyroid peroxidase antibody titers." (PMID 32582023, 2020).
hypothyroidism (continued). "In thyroid autoimmune disorders such as Hashimoto’s thyroiditis (hypothyroidism) and Graves’ disease (hyperthyroidism), autoantibodies against TPO are produced (TPO-Ab), with the access of immune cells to TPO thought to be due to destruction of thyrocytes." (PMID 32678000, 2020). "Based on the information published in previous studies, we found that the increased expressions of TG, TG-Ab, and TPO-Ab in the serum are important predictors of hypothyroidism." (PMID 32461982, 2020). "Those on thyroxine replacement, with overt hypothyroidism, or with positive anti-thyroperoxidase (TPO) antibody were excluded." (PMID 32873266, 2020). "Some previous studies have demonstrated that the concentration of thyroid-associated antibodies (i.e., antithyroid peroxidase antibody (TPO-Ab) and antithyroglobulin antibody (TG-Ab)) can be correlated with hypothyroidism." (PMID 32461982, 2020). "The rate of permanent hypothyroidism was found to be significantly higher in anti-TPO and anti-Tg positive patients (p: 0.02 and p: 0.027 respectively)." (PMID 32555998, 2020). "This is consistent with our findings which showed that TG, TG-Ab, and TPO-Ab are independent predictors of hypothyroidism." (PMID 32461982, 2020). "Hashimoto's thyroiditis is a diversified autoimmune disorder where the presence of anti-thyroid peroxidase (anti-TPO) and anti-thyroglobulin antibodies dial the functioning of the thyroid gland causing transient hyperthyroidism and eventual hypothyroidism." (PMID 33527061, 2020). "Two patients developed primary hypothyroidism: one patient developed anti-TPO antibody-positive hypothyroidism after the third cycle of treatment, while the other patient gradually developed hypothyroidism, needing hormone replacement 3.5 years after PRRT." (PMID 33551992, 2020). "In the patients, 30 (10.4%) had hypothyroidism, 9 (3.2%) hyperthyroidism, 249 (86.4%) thyroid function, and 5 (1.7%) positive anti-TPO test result." (PMID 32190224, 2020). "Both subclinical/overt hypothyroidism and hyperthyroidism showed high percentage of subjects who had anti-TPO prior to the onset of thyroid dysfunction compared to the combined control group." (PMID 31467701, 2019). "Another cross-sectional study published in 2011 (adults >35 years old, in Armenia city) determined the frequency of hypothyroidism and its relationship with anti-TPO antibodies and elevated urinary iodine among 437 individuals (mostly females)." (PMID 31061736, 2019). "126/152 (82.9%) subjects in group A1 had either anti-TPO or anti-Tg prior to the onset of subclinical/overt hypothyroidism compared to 111/152 (73.0%, p= 0.0522) with anti-TPO and 83/152 (54.6%, p<0.0001) with anti-Tg." (PMID 31467701, 2019). "The later 3 groups (parallel, following, and never) were combined to create the control group (41/152 (27.0%)) to compare the significance of anti-TPO occurring prior to the onset of subclinical/overt hypothyroidism." (PMID 31467701, 2019). "In a Danish study, 45% of the patients, with a mean age of 36.7 years, were revealed as positive for TPO-AB; hypothyroidism was found in 33%." (PMID 31627185, 2019). "Both subclinical/overt hypothyroidism and hyperthyroidism showed a significantly higher percentage of subjects who had anti-TPO prior to the onset of thyroid dysfunction compared to the combined control group." (PMID 31467701, 2019). "Of the 4614 women, 61.8% of women with hypothyroidism and 49.4% with subclinical hypothyroidism had an elevated thyroid peroxidase antibody, as compared with 8.2% with euthyroidism and 12.5% with hyperthyroidism." (PMID 29463525, 2018). "HT is characterized by intrathyroidal monocyte infiltration along with rising serum autoantibodies, such as anti-thyroglobulin antibody (anti-Tg) and anti-thyroid peroxidase antibody (anti-TPO), and is the leading cause of hypothyroidism worldwide." (PMID 30373627, 2018).
hypothyroidism (continued). "Elevated ATA, especially anti-TPO Ab titers were shown to correlate with the development of overt hypothyroidism." (PMID 29884162, 2018). "Changes in level of anti-TPO correlated positively with the development of hypothyroidism and an increased inflammatory reaction." (PMID 30384852, 2018). "Secondary outcome measures: dose of levothyroxine required to treat hypothyroidism, thyroid peroxidase antibodies (anti-TPO), and anti-thyroglobulin antibodies (anti-Tg)." (PMID 30532779, 2018). "According to logistic regression, hypothyroidism increased the rate of preterm delivery 1.46 times, and presence of anti-TPO raised it 2.62 times, However, the difference wasn’t statistically significant (p = 0.06 and p = 0.05 respectively)." (PMID 30288165, 2017). "Lab tests showing high TSH and low free T4 are indicative of biochemical hypothyroidism and, if present, additional testing for thyroid antibodies such as thyroid peroxidase (TPO) antibody is warranted." (PMID 29162153, 2017). "Although it was shown that isoflavones are able to inactivate TPO in vitro, the in vivo study excluded their direct relationship with hypothyroidism." (PMID 29271877, 2017). "In the serum, elevated TPO-Abs were found which pointed to Hashimoto thyroiditis being responsible for the hypothyroidism." (PMID 27688922, 2016). "The present study showed low iodine intake is not the sole etiological candidate for hypothyroidism disorder in India as approximately half of the hypothyroidism patients included in this study were found to have presence of anti-TPO antibodies." (PMID 26963610, 2016). "Considering the atrophic gland in thyroid ultrasound, it is likely that serum TPO-Abs had been elevated already a couple of years prior to the manifestation of overt hypothyroidism and delirious mania." (PMID 27688922, 2016). "We analyzed the presence of anti-TPO antibodies in the plasma samples of 84 hypothyroidism patients and 62 controls by ELISA." (PMID 26963610, 2016). "It was found that the decrease of TPO-Ab in euthyroidism HT-Tx group and the decrease of TG-Ab in hypothyroidism HT-Tx were more obvious, respectively." (PMID 27721890, 2016). "Documenting high serum concentrations of anti-thyroid peroxidase (anti-TPO) and/or anti-thyroglobulin (anti-TG) autoantibodies is sufficient to diagnose chronic autoimmune thyroiditis as the cause of a patient's hypothyroidism." (PMID 27429616, 2016). "Our data, therefore, argue for a decline of IDD during the last decade, while the prevalence of thyroid diseases related to iodine repletion such as hypothyroidism or positive anti-TPO Abs was stable or even decreased during that time period." (PMID 27833458, 2016). "The level of anti-TPO antibody and the duration of hypothyroidism before gestation were significantly different between the two groups (P= 0.0001 and P= 0.001);." (PMID 26573046, 2015). "While the adverse effects of SCH accompanied with positive TPO antibodies or overt hypothyroidism on pregnancy outcome are well known, however there is controversy on negative impact of SCH without autoimmunity on pregnancy outcomes." (PMID 26494985, 2015). "A proportion of 31.3% and 27% of the patients with hypothyroidism were found positive to anti-TG or anti-TPO, respectively, while 47.9% of the patients were positive in one or both thyroid specific autoantibodies." (PMID 25003133, 2014). "Lymphocytic infiltration of TPO antibodies during early stages of development can be seen as predictor for the development of hypothyroidism in future." (PMID 25168993, 2014). "One of the important complications during pregnancy can be hypothyroidism, so measurement of TPO autoantibodies is recommended strongly." (PMID 25168993, 2014). "If first trimester of pregnancy shows highest levels of TPO autoantibodies, it can lead to development of hypothyroidism in the postpartum period." (PMID 25168993, 2014).
hypothyroidism (continued). "Given the increased level of TSH and anti-TPO, her hypothyroidism was most likely secondary to Hashimoto's disease rather than pituitary infiltration." (PMID 24106505, 2013). "On linear regression in euthyroid (after exclusion for hypothyroidism) women with anti-TPO positivity, the percentage of live birth was found to correlate with level of TPO antibody (R=0.17, P=0.01)." (PMID 23802061, 2013). "In the healthy control group, comprised of pregnant women without a history of abortion, the prevalence of subclinical hypothyroidism was 24% and TPO positivity was 18% (P=0.70)." (PMID 23802061, 2013). "There is a general consensus that subclinical hypothyroidism detected during pregnancy should be treated with l-thyroxine, particularly in the presence of thyroid peroxidase antibodies (TPO-Abs) (12, –, 14)." (PMID 24217906, 2013). "These risks are increased in the whole spectrum of hypothyroidism, including isolated TPO positivity, subclinical hypothyroidism and overt hypothyroidism." (PMID 23802061, 2013). "1.1% of the overall sample was affected by hypothyroidism, 16.6% had an anti-TPO value above the normal cut-off (anti-TPO+)." (PMID 15317653, 2004). "It has been hypothesized that the presence of antithyroid antibodies such as TPO and thyroglobulin antibodies could be a favorable factor leading to hypothyroidism." (PMID 40361497, 2025). "Knowing whether levels of anti-TPO, TRAb and other factors affect relapse rate or hypothyroidism after treatment for GD can help the physician make informed decisions on choice of treatment." (PMID 40255503, 2025). "Elevated levels of anti-thyroperoxidase (anti-TPO) and anti-thyroglobulin (anti-Tg) antibodies frequently accompany hypothyroidism, suggesting an autoimmune basis that may contribute to persistent urticarial symptoms." (PMID 40075855, 2025). "The presence of anti-thyroid peroxidase antibodies or anti-thyroglobulin antibodies is associated with the development of hypothyroidism; however, these test data are not routinely measured in clinical practice." (PMID 40190852, 2025). "Importantly, a statistically significant association was observed between hypothyroidism and other autoimmune conditions, particularly celiac disease, as all anti-TTG-positive patients were also anti-TPO positive." (PMID 41280993, 2025). "This case highlights the diagnostic challenges of negative TPO-Ab and TgAb hypothyroidism, which are often misdiagnosed as Hashimoto's thyroiditis." (PMID 40900474, 2025). "Although thyroid peroxidase antibodies (anti-TPO) are prevalent in patients with GD, their role in driving relapse or hypothyroidism after treatment in patients with GD remains unclear." (PMID 40255503, 2025). "However, according to that theory, patients with anti-TPO should also be more likely to develop hypothyroidism." (PMID 40255503, 2025). "In the study reported by Elgazar and colleagues, 200 patients with Type-II DM, 11.1% of women with overt hypothyroidism, 57.2% were positive for thyroid antibodies, which were 42.9% positive for anti-TPO alone, 0% for anti-TG alone, and 14.3% positive for both antibodies." (PMID 40735558, 2025). "Anti-TPO antibodies can be present in Graves’ disease and may predict the eventual development of hypothyroidism." (PMID 40772166, 2025). "Second, Th1 cytokines (e.g., IFN-γ, TNF-α) mediate thyroid follicular cell apoptosis, triggering transient thyrotoxicosis, followed by Hashimoto-like pathology with elevated thyroid peroxidase antibodies (TPOAb), ultimately progressing to permanent hypothyroidism." (PMID 40264768, 2025). "Our patient also had a history of hypothyroidism with positive anti-TPO antibodies." (PMID 41170251, 2025). "Based on the findings of the current study, it is not necessary for clinicians to consider anti-TPO levels at GD diagnosis as a risk factor for relapse or hypothyroidism after ATD." (PMID 40255503, 2025).